GCH1 (GTP cyclohydrolase 1)
Diseases named in the same sentence as GCH1 in open-access papers (continued):
Sharing a sentence is not in itself a finding about the gene and the disease.
tumor (35 papers, 2016 to 2026). "The use of GCH1 inhibitors suppress tumor growth and induce a switch in tumor immune response from M2 to M1 polarization of tumor associated macrophages." (PMID 36505465, 2022). "Decreased GCH1 expression is significantly associated with a higher Barcelona Clinic Liver Cancer stage and larger tumor size." (PMID 34502450, 2021). "There was uniform upregulation of this gene cluster (which included Adc, Nos2, Ass1, Gch1, Asl and Got1) in both tumor-associated MP and MG and Gr1+ cells." (PMID 27936099, 2016). "Next, the critical genes' signaling pathways, as well as the putative molecular processes by which GCH1 and H1.2 promote tumor growth, were investigated." (PMID 41583517, 2026). "The average distance between GCH1-CD163 in tumor cells and immune cells significantly differed between the Low GCH1 and High GCH1 groups (19.24 μm vs. 159.80 μm, P = 0.0015)." (PMID 41583517, 2026). "Specifically, genes such as TRIM71, DBH, HP, FER1L4, and GCH1 exhibited dynamic and progressive expression changes along tumor grades, with significant increases in Grade 4 tumors compared to Grade 1 (Wilcoxon test, adj." (PMID 41347690, 2025). "Several studies have confirmed that GCH1 suppression and erastin co-treatment in vivo synergistically suppressed tumor growth." (PMID 40143150, 2025). "More importantly, GNA influenced redox levels by reducing GCH1 expression, which further promoted ferroptosis of tumor cells, as also confirmed by rescue experiments." (PMID 40143150, 2025). "Immunohistochemical analysis of Ki67 expression showed that GCH1 overexpression reversed the GNA inhibitory effects against Ki67 expression in tumor tissues." (PMID 40143150, 2025). "Accordingly, therapeutic strategies based on the key targets of ferroptosis, such as GPX4, ferroptosis suppressor protein 1 (FSP1) and GCH1, are capable of reversing cancer drug resistance and interrupting tumour progression." (PMID 39163517, 2024). "ITGA5 and SLC7A1 were found to be overexpressed in CC tumor tissues and were associated with a worse prognosis, except for LCK, GCH1 and TNFRSF9." (PMID 38903179, 2024). "GCH1 expression correlated with lymph node metastases, vessel invasion, and the pathological tumor stage." (PMID 39723384, 2024). "We considered that GCH1 is involved in enhancing cell proliferation and suppressing cell death and that GCH1 overexpression induces a decrease in tumor cell proliferation, whereas decreased GCH1 expression induces an increase in tumor cells." (PMID 39723384, 2024). "Ki67 immunohistochemical staining showed a decreased percentage of proliferating (Ki67+) tumor cells after the administration of niraparib and DAHP, suggesting that the combination of GCH1 inhibitors and niraparib potently reined back tumor growth." (PMID 36793373, 2023). "Subsequently, the enhancement of the tumor-killing effect of PARP inhibitors induced by GCH1 suppression using siRNA and GCH1 inhibitor was validated by flow cytometry in vitro." (PMID 36793373, 2023). "Small-interfering RNAs (siRNAs) were applied to transiently silence GCH1 in the MDA-MB-231 tumor cell line." (PMID 36793373, 2023). "Reduced GCH1 activity can result in tumor vascularization and lowering of NOS, which can produce superoxide." (PMID 36908807, 2022). "Multivariate analysis, taking into account of estrogen receptor (ER) status as a binary covariate with tumor grade, size, nodal status and menopause, showed a significant independent correlation between high GCH1 and worse survival rate." (PMID 26814432, 2016). "Essentially, there was a statistically significant correlation between GCH1 and Ang-1 expression, emphasizing the potential clinical relevance of a GCH1/Ang-1 connection in tumor stroma." (PMID 26814432, 2016). "However, GCH1 overexpression reversed the GNA inhibitory effects upon tumor weight and tumor volume." (PMID 40143150, 2025). "GCH1 overexpression reversed GNA inhibitory effects against tumor growth." (PMID 40143150, 2025).
tumor (continued). "Our findings indicated that GCH1 is similarly downregulated in tumor tissues." (PMID 38903179, 2024). "In summary, GCH1 may serve as a promising target to sensitize tumor cells to PARP inhibitors and enhance the antitumor efficacy." (PMID 36793373, 2023). "Taken together, GCH1 inhibitor could augment the sensitivity of tumor cells to PARP inhibitor in vivo." (PMID 36793373, 2023). "GCH1 inhibitor and erastin co-treatment in vivo synergistically inhibited tumor growth in CRC." (PMID 35223839, 2022). "Interestingly, the intra-tumor Gch1 gene expression was strongly inhibited in 96 h-SPS–treated tumors, but not in RPMI group, when compared with the normal saline control group (p< 0.001)." (PMID 36908807, 2022). "Furthermore, the protection of adjacent cells mediated by membrane-permeable BH4 and the dense three-dimensional spheroids induced by GCH1 further supplement ferroptosis resistance in tumor progression." (PMID 32908642, 2020). "Similarly, GCH1 has been shown to promote tumor growth, angiogenesis, and reduce antitumor immune responses." (PMID 26460926, 2016). "Therefore, we hypothesized that GNA could induce ferroptosis of tumor cells by inhibiting GCH1 expression and disrupting tumor REDOX homeostasis." (PMID 40143150, 2025). "Although we propose a rational therapeutic strategy to render niraparib more effective in killing tumor cells that can be further tested in the clinic, whether GCH1 could be a biomarker for sensitivity to PARP inhibitor treatment still warrants further investigations." (PMID 36793373, 2023). "Additionally, we have demonstrated in vivo using the PDX model that targeting GCH1 could potentiate the sensitivity of tumor cells to PARP inhibitors and markedly inhibit tumor growth without producing excessive toxic side effects." (PMID 36793373, 2023). "The in vivo experimental data showed that GCH1 overexpression reversed GNA inhibitory effects against tumor growth, suggesting that GNA suppressed malignant progression regarding NSCLC through targeting GCH1 and inducing ferroptosis." (PMID 40143150, 2025). "Our experimental evidence indicated that pharmacological inhibition of GCH1 using DAHP, in combination with the ferroptosis inducer RSL3, efficiently suppressed LLC tumor growth and prolonged the survival of tumor-bearing mice." (PMID 40619484, 2025). "Thus, GCH1 may possess undiscovered functions related to tumor survival and progression." (PMID 39723384, 2024). "In this study, the inflammatory response genes (ITGA5, LCK, GCH1, TNFRSF9 and SLC7A1) play different role in immune tumor microenvironment." (PMID 38903179, 2024). "The tumor volumes and sizes were obviously decreased after circLRFN5 overexpression, while they increased after PRRX2 overexpression or GCH1 overexpression, respectively." (PMID 36266731, 2022). "GCH1 was reported as a ferroptosis suppressor via generating antioxidant tetrahydrobiopterin (BH4) and regulated GBM growth and tumor-initiating cell maintenance." (PMID 36266731, 2022). "Additionally, 2,4-diamino-6-hydroxypyrimidine (DAHP)-mediated suppression of GCH1 lowered IDO1 expression, inhibited tumor growth, and improved tumor response to PD-1 blocking immunotherapy." (PMID 39371092, 2024). "Inhibition of GCH1 by 2,4-diamino-6-hydroxypyrimidine could block IDO1 activity, halt tumor growth, and enhance the tumor response to anti-PD-1 immunotherapy." (PMID 37040510, 2023). "Finally, the relationship of GCH1 to homologous recombination repair was revealed, and we proved the superiority of the combination of PARP inhibitors and GCH1 inhibition in tumor killing in vitro and in vivo." (PMID 36793373, 2023). "Gch1-Spr-BH4 and NO/ROS imbalance axis should be examined in 96 h-SPS–treated tumors in the future, as a possible molecular mechanism involved in the induction of tumor cells death and inhibition of tumor development in the present study." (PMID 36908807, 2022).
tumor (continued). "Moreover, GCH1 inhibition has been shown to prevent the production of BH4 and suppress tumor development via directly killing tumor cells and inhibiting angiogenesis." (PMID 36908807, 2022). "To obtain an overall view of the intra-tumor iron levels, we compared the total iron in 96 h-SPS–treated tumor to normal saline reference group, where we saw a significant reduction in gene expression of Gch1-Spr axis." (PMID 36908807, 2022). "In addition, FSP1, GCH1, and IFN-γ are innovative targets that can be exploited for tumor resistance." (PMID 32908642, 2020). "The GCH1 gene was also highly expressed in patients with ER or progesterone receptor (PR)-negative tumor status." (PMID 26814432, 2016). "The System Xc–/GSH/GPX4 axis, DHODH–ubiquinol (CoQH2) system, FSP1–CoQ10 axis, GTP cyclohydrolase-1 (GCH1)–tetrahydrobiopterin (BH4) axis, and sex hormones can inhibit ferroptosis, and the inhibition of related molecular pathways is an important strategy to induce ferroptosis in tumor cells." (PMID 39399506, 2024). "The apoptosis of tumor cells was not significantly changed upon GCH1 silencing." (PMID 36793373, 2023).
cardiovascular disease (14 papers, 2012 to 2022). "Small molecules that mimic this allosteric activation of GCH1 represent a potential novel therapy to treat a diverse range of cardiovascular diseases underpinned by limited NO and/or enhanced oxidative stress." (PMID 29963647, 2018). "A number of studies have looked at cardiovascular disease in relation to the GCH1 genetic variation." (PMID 25369080, 2014). "GCH1 is considered as a major factor in maintaining nitric oxide synthetase (NOS) function and normal blood pressure, and its inhibition can increase blood pressure due to NOS uncoupling, which is found in many cardiovascular diseases such as hypertension and atherosclerosis." (PMID 28585439, 2017). "Therefore, targeting vascular Gch1 and BH4 biosynthesis may provide a novel therapeutic target for the prevention and treatment of microvascular dysfunction in patients with cardiovascular disease." (PMID 28128438, 2017).
infection (6 papers, 2013 to 2025). The state of being infected such as from the introduction of a foreign agent such as serum, vaccine, antigenic substance or organism. "Interestingly, the infection-induced downregulation of DHFR with minimal change in GCH1 expression suggests that endothelial BH4 deficiency primarily results from the salvage pathway (increased oxidized biopterins over BH4 levels) rather than decreased de novo synthesis." (PMID 41294830, 2025). "In contrast, GCH-1 mRNA exhibited a slight increase following infection, which gradually returned to near-basal levels; however, these changes were not statistically significant (p > 0.05)." (PMID 41294830, 2025). "The percentage of death in irradiated HELF and BEAS-2B cells was significantly decreased after infection with Ad-GCH1." (PMID 38689083, 2024). "Infection with Ad-GCH1 or the addition of BH4 significantly decreased the luciferase activity of the Smad2/3-responsive reporter following radiation." (PMID 38689083, 2024). "In nonirradiated left lung tissues, ROS, MDA and NO levels were generally unchanged by Ad-GCH1 infection or BH4 supplementation." (PMID 38689083, 2024). "Strikingly, the expression of GCH1 was significantly up-regulated as early as 24 h post-infection, which was inconsistent with the LDH release assay." (PMID 38790682, 2024). "As expected, infection with WT GCH1 or the mutants induced GCH1 expression via differential phosphorylation, which did not significantly affect GFRP expression." (PMID 38689083, 2024). "Infection with a GCH1-overexpressing adenovirus (Ad-GCH1) significantly increased GCH1 protein levels in HELF and BEAS-2B cells." (PMID 38689083, 2024). "This revealed that M5 inhibited ferroptosis via the GCH1/BH4 pathway in the early stage of infection, promoting its intracellular proliferation, but induced ferroptosis through the GPX4/GSH pathway to facilitate its escape and spread in the late stage of infection." (PMID 40606156, 2025). "The results showed that Ad-GCH1 infection did not affect cellular NO levels in HELF or BEAS-2B cells in the absence of radiation." (PMID 38689083, 2024). "Exposure to 20 Gy of irradiation significantly increased ROS levels in the right lung, whereas infection with Ad-GCH1 but not Ad-NC reduced ROS levels." (PMID 38689083, 2024).
genetic disorders (4 papers, 2009 to 2025). "This is the first GCH1 regulatory substitution reported to act at a post-transcriptional level, increasing the list of genetic diseases caused by abnormal translation and reaffirming the importance of investigating potential regulatory substitutions in genetic diseases." (PMID 24124602, 2013). "Consistent with previous reports showing beneficial effects on pain relief in patients with GCH1 genetic disorders, our findings strongly suggest that GCH1 modulation can be effectively developed as a clinically applicable gene therapy strategy to treat neuropathic pain." (PMID 19922668, 2009).
metabolic disorder (4 papers, 2019 to 2025). "Proteomic detection data showed that GNA treatment resulted in a metabolic disorder, and GCH1 is a rate-limiting enzyme." (PMID 40143150, 2025). "In particular, a mutation of GTP cyclohydrolase 1 (GCH1), the rate-limiting enzyme of BH4 biosynthesis, is a major genetic cause of BH4 deficiency found in different types of neurological and metabolic disorders." (PMID 31533268, 2019).
neurological diseases (3 papers, 2012 to 2022). "GCH1 might involve in the protein translation, fatty acid metabolism and mitochondrial function which might provide new mechanisms for its beneficial effects in cardiovascular and neurological diseases." (PMID 22479495, 2012).
bacterial infection (2 papers, 2018 to 2023). "However, our results showed that Gch1 levels were elevated in the lungs of mice induced by LPS to mimic lung injury caused by bacterial infection compared to healthy controls." (PMID 38071255, 2023). "Gene expression analysis reveals that Gch1 deficient macrophages have altered inflammatory response, lysosomal function, cell survival and cellular metabolism, thereby enhancing the control of bacterial infection." (PMID 30573728, 2018).
neurodegenerative disease (2 papers, 2022 to 2025). A disorder of the central nervous system characterized by gradual and progressive loss of neural tissue and neurologic function. "The role of GCH1 gene in dopaminergic pathways suggests a potential link to broader neurodegenerative diseases, warranting further investigation into the underlying mechanisms." (PMID 39801809, 2025).
psychiatric disorder (2 papers, 2016 to 2022). A disorder characterized by behavioral and/or psychological abnormalities, often accompanied by physical symptoms. "The GCH1 gene has been studied in terms of its association with psychiatric disorders and cognitive function." (PMID 26215833, 2016).
GCH1 also shares sentences with these, for which no sentence is quoted: movement disorder (4 papers); Anxiety (3); Intellectual disability (3); -Deficient (2); amyotrophic lateral sclerosis (2); chronic pancreatitis (2); dyslipidemia (2); epilepsy (2); frontotemporal dementia (2); Gaucher disease (2); generalized dystonia (2); neuroblastoma (2); schizophrenia (2); Segawa syndrome (2); viral infection (2); abdominal obesity-metabolic syndrome (1); acute lymphoblastic leukemia (1); acute pancreatitis (1); Adult onset (1); Allergy (1); atrial fibrillation (1); autism spectrum disorder (1); autoimmune disease (1); autonomic dysfunction (1); bacterial sepsis (1); bipolar disorder (1); bladder cancer (1); blepharospasm (1); breast tumor (1); cerebellar ataxia (1).
A further 63 diseases each share a sentence with GCH1 in 1 paper.